TRAPPC11 (trafficking protein particle complex subunit 11)
Description:
Involved in endoplasmic reticulum to Golgi apparatus trafficking at a very early stage.
Synonyms: C4orf41; FLJ12716; gry; foigr; LGMD2S; LGMDR18
Tractability: PROTAC: ubiquitination databases record sites on it; its protein half-life has been measured.
Gene: Protein-coding gene on chromosome 4 (183,659,267 to 183,713,594, forward strand). Ensembl gene ENSG00000168538.
Subcellular location: Golgi apparatus; Golgi apparatus, cis-Golgi network
Subcellular location (Human Protein Atlas): Cytosol; Vesicles
Pathways (Reactome):
Vesicle-mediated transport: RAB GEFs exchange GTP for GDP on RABs
Gene Ontology:
Molecular function: protein binding
Biological process: constitutive secretory pathway; endoplasmic reticulum to Golgi vesicle-mediated transport; Golgi organization; regulation of protein complex stability; COPII vesicle coating
Cellular component: Golgi apparatus; TRAPP complex; cytoplasm; cytosol; TRAPPIII protein complex
Genetic constraint (gnomAD): Loss-of-function variants: 80 observed, 118.04 expected, observed/expected ratio (o/e) 0.68, 90% interval 0.56 to 0.82. The upper end of that interval is the gene's LOEUF score, 0.82, which puts it in group 3 of 6, group 1 being the genes least tolerant of losing a copy. Missense variants: 996 observed, 1,102.4 expected, observed/expected ratio (o/e) 0.9, 90% interval 0.86 to 0.95. Synonymous variants: 363 observed, 386.99 expected, observed/expected ratio (o/e) 0.94, 90% interval 0.86 to 1.02.
Gene-disease validity (ClinGen):
ClinGen rates the evidence that TRAPPC11 causes each of these diseases.
autosomal recessive limb-girdle muscular dystrophy (autosomal recessive): Definitive. Autosomal recessive form of limb-girdle muscular dystrophy.
Homologues: Orthologues: chimpanzee TRAPPC11 (99% identical), macaque TRAPPC11 (97% identical), guinea pig TRAPPC11 (96% identical), dog TRAPPC11 (96% identical), rabbit TRAPPC11 (96% identical), pig TRAPPC11 (95% identical), mouse Trappc11 (94% identical), rat Trappc11 (94% identical), tropical clawed frog trappc11 (86% identical), zebrafish trappc11 (78% identical), Drosophila melanogaster gry (32% identical), Caenorhabditis elegans trpp-11 (27% identical).
Diseases named in the same sentence as TRAPPC11 in open-access papers:
TRAPPC11 is named in the same sentence as 31 diseases in open-access papers, as found by Europe PMC text mining. Sharing a sentence is not in itself a finding about the gene and the disease. The quoted sentences say what the papers report.
limb-girdle muscular dystrophy (5 papers, 2015 to 2024). Limb-girdle muscular dystrophy (LGMD) is a heterogeneous group of muscular dystrophies characterized by proximal weakness affecting the pelvic and shoulder girdles. "For example, the TRAPPC2 subunit is the only subunit where pathogenic variants lead to a skeletal disorder, whilst TRAPPC11 has a unique limb girdle muscular dystrophy phenotype in humans." (PMID 39769094, 2024). "The TRAPPC11 subunit has been implicated in muscle disease by virtue of homozygous and compound heterozygous deleterious mutations being identified in individuals with limb girdle muscular dystrophy and congenital muscular dystrophy." (PMID 29855340, 2018). "In humans, TRAPPC11 mutations have been reported in only three families showing limb-girdle muscular dystrophy (LGMD) or myopathy with movement disorders and intellectual disability." (PMID 26322222, 2015).
Intellectual disability (4 papers, 2014 to 2025). "Mutations have previously been reported in several members of the TRAPP complex of proteins, including TRAPPC2, TRAPPC9 and TRAPPC11, resulting in disorders involving skeletal abnormalities, intellectual disability, speech impairment and developmental delay." (PMID 29391579, 2018).
Muscular dystrophies (3 papers, 2014 to 2025). "Since TRAPPC11 mutations have been reported in a number of individuals suffering from a muscular dystrophy, and these individuals also display membrane trafficking defects in cultured fibroblasts, this gene should be considered in the diagnostic evaluation of patients with CMD." (PMID 29855340, 2018). "TRAPPC11 does not appear in the ranking, as it was annotated with only two GO terms that are not significant for muscular dystrophies ("vesicle-mediated transport" and "Golgi apparatus"), it has no annotation for pathways or phenotypes, and its two protein motifs are unique in the genome." (PMID 25353622, 2014).
diabetes (1 paper, 2023). "The only patient with the rare subtype LGMD-R18/LGMD2S had TRAPPC11 mutations; had a later onset than those previously reported, and presented with proximal‒distal muscle weakness, walking aid dependency, fatty liver disease and diabetes at 33 years of age." (PMID 37974208, 2023).
Gaucher disease (1 paper, 2020). Gaucher disease (GD) is a lysosomal storage disorder encompassing three main forms (types 1, 2 and 3), a fetal form and a variant with cardiac involvement (Gaucher disease - ophthalmoplegia - cardiovascular calcification or Gaucher-like disease). "Subsequently, several rare inherited metabolic disorders have been successfully investigated in zebrafish revealing underlying mechanisms and identifying novel therapeutic targets, including methylmalonic acidemia, Gaucher’s disease, maple urine disorder, hyperammonemia, TRAPPC11-CDGs, and others." (PMID 32971894, 2020).
progressive supranuclear palsy (1 paper, 2025). A rare late-onset neurodegenerative disease characterized by supranuclear gaze palsy, postural instability, progressive rigidity, and mild dementia. "DNA methylation at cg21836426, annotated to RWDD4A (5’UTR/ first exon) and C4orf41 (alternative gene name TRAPPC11) (TSS1500), was previously associated with progressive supranuclear palsy, a form of tau-related dementia, in adults." (PMID 39844285, 2025).
steatosis (1 paper, 2015). Increased lipid within the cytoplasm of cells. "Zebrafish with a mutation in the TRAPPC11 orthologue showed hepatomegaly with steatosis and defects in visual system development." (PMID 26322222, 2015). "A loss-of-function mutation in the zebrafish TRAPPC11 orthologue is characterized by hepatomegaly with steatosis, thereby named foie gras mutant, and by defects in visual system development." (PMID 26322222, 2015).
neurodevelopmental disorder (1 paper, 2018). A behavioral and cognitive disorder with onset during the developmental period that involves impaired or aberrant development of intellectual, motor, or social functions. "In summary, TRAPPC6A potentially adds to a growing list of TRAPP complex proteins (TRAPPC2, TRAPPC9, TRAPPC11), including the closely related TRAPPC6B, involved in neurodevelopmental disorders." (PMID 29391579, 2018).
TRAPPC11 also shares sentences with these, for which no sentence is quoted: congenital muscular dystrophy (4 papers); myopathy (4); Ataxia (2); movement disorder (2); Cerebral atrophy (1); cone-rod dystrophy (1); congenital cataracts (1); developmental delay (1); dysferlinopathy (1); dystroglycanopathies (1); Epileptic encephalopathy (1); fatty liver disease (1); glycosylation disorders (1); Hyperammonemia (1); left ventricular hypertrophy (1); limb girdle muscular dystrophy type 2S (1); metabolic disorders (1); methylmalonic acidemia (1); microcephaly (1); mitochondrial DNA depletion syndrome (1); Progressive microcephaly (1); rhabdomyolysis (1); Spastic tetraplegia (1).